CX3CR1 (C-X3-C motif chemokine receptor 1)
Diseases named in the same sentence as CX3CR1 in open-access papers (continued):
Sharing a sentence is not in itself a finding about the gene and the disease.
vitamin D deficiency (2 papers, 2017 to 2023). A nutritional condition produced by a deficiency of VITAMIN D in the diet, insufficient production of vitamin D in the skin, inadequate absorption of vitamin D from the diet, or abnormal conversion of vitamin D to its bioactive metabolites. "Among patients with vitamin D deficiency, we also found higher percentages of patrolling monocytes (CD14dimCD16+), which typically express high levels of CX3CR1, and lower percentages of the classical monocyte subset (CD14++CD16-) that typically express CCR2 overall." (PMID 28464004, 2017). "In univariate logistic regression models, we found that increased expression of CX3CR1+ (p <0.01) and decreased expression of CCR2+ (p < 0.01) were significantly associated with vitamin D deficiency." (PMID 28464004, 2017). "After adjustment, greater expression of CX3CR1 and lower expression of CCR2 remained significantly associated with vitamin D deficiency." (PMID 28464004, 2017). "In fully adjusted models associations with vitamin D deficiency persisted for CCR2+ and CX3CR1+." (PMID 28464004, 2017).
acute GVHD (1 paper, 2024). "The high expression of CX3CR1 on the surface of CD8+T cells and the overexpression of its ligand CX3CL1 in the intestinal mucosa of patients with acute GVHD suggest the critical role of the CX3CR1/CX3CL1 axis in intestinal infiltration and damage during acute GVHD." (PMID 39840040, 2024).
alcohol use disorders (1 paper, 2024). "The restored CX3CL1/CX3CR1 signaling, which is directly linked to the regulation of neuron–glial communication, offers potential protection against the neuroinflammatory conditions frequently observed in neuropsychiatric disorders, including alcohol use disorders." (PMID 39063614, 2024).
alcoholic liver diseases (1 paper, 2018). A disorder caused by damage to the liver parenchyma due to alcohol consumption. "CX3CR1 could be a specific marker for separating resident macrophage subsets and may be a novel therapeutic target in alcoholic liver disease." (PMID 30305672, 2018). "In the present study, we investigated the role of CX3CR1 in the functional and phenotypic polarization of hepatic macrophages from circulating monocytes using an in vitro differentiation model and an in vivo alcoholic liver disease model." (PMID 30305672, 2018). "Therefore, the interplay between CX3CR1 and CX3CL1 might affect the progression of alcoholic liver disease." (PMID 30305672, 2018). "However, the role of CX3CR1 in alcoholic liver disease has not been studied." (PMID 30305672, 2018).
allergic contact dermatitis (1 paper, 2020). An inflammatory skin condition caused by an immune response to direct contact between the skin and an allergen. "Targeting macrophages or CX3CR1 could be a new therapeutic strategy for the treatment of allergic contact dermatitis." (PMID 33036460, 2020).
Anorexia (1 paper, 2010). Lack of desire to eat (loss of appetite). "Specifically, while aged mice show exaggerated anorexia and weight loss after LPS injection, CX3CR1-/- mice do not." (PMID 21167054, 2010). "Thus, a specific increase of IL-1β in CX3CR1-/- mice without a concomitant exaggeration of TNFα may enhance the behavioral effects of LPS without causing exaggerated anorexia and weight loss." (PMID 21167054, 2010).
ascending aortic aneurysm (1 paper, 2025). "As a result, RS504393 also efficiently suppressed Ly6Chi monocyte recruitment and subsequent CX3CR1+ macrophage accumulation in aneurysmal aortas, thereby ameliorating the progression of aortic root and ascending aortic aneurysms in Fbn1C1041G/+ mice." (PMID 39817456, 2025). "In accordance, transthoracic echocardiography showed that DT-induced elimination of CX3CR1+ macrophages/monocytes greatly ameliorated both aortic root and ascending aortic aneurysm progression as well as related aortic wall pathologies in Cx3cr1-CreERT2iDTRF/+Fbn1C1041G/+ mice." (PMID 39817456, 2025). "In accordance, either knockdown of Tnfα or Igf1 in CX3CR1+ macrophages reduced vascular inflammation, as evidenced by the downregulation of Mcp1, Il6, and Cxcl2, and subsequently ameliorated both aortic root and ascending aortic aneurysm progression as well as related aortic wall pathologies." (PMID 39817456, 2025).
Ataxia (1 paper, 2022). Ataxia refers to impaired coordination of voluntary muscle movement. "In both CX3CR1 cell ablation and microglia ablation mice, we did not notice the obvious motor dysfunction in the current study or previous studies, unlike a recent report suggesting that microglial ablation induces neurodegeneration and ataxia." (PMID 36289499, 2022).
Bovine mastitis (1 paper, 2023). INFLAMMATION of the UDDER in cows. "For instance, the differential expression of genes (CX3CR1, RHOH, LPAR5, and GATA3) overlapped with dMHB discriminant signatures related to SC subclinical mastitis have been found relevant to immune responses to bovine mastitis." (PMID 37373515, 2023).
breast tumors (1 paper, 2022). "The chemokine receptor CX3CR1 is over-expressed in both primary and metastatic breast tumors." (PMID 35754051, 2022). "CCR3 and CX3CR1 were differentially expressed between Black versus White, and CCR6, CCRL2, and CXCR4 between Asian versus White breast tumors." (PMID 35754051, 2022).
Burkitt lymphoma (1 paper, 2009). A rare form of malignant mature B-cell non-Hodgkin lymphoma. "Expression of CX3CR1 mRNA was never detected in the Raji Burkitt lymphoma cell line." (PMID 20041188, 2009).
carcinoma in situ (1 paper, 2023). "This increase in CX3CR1 levels is associated with anti-tumor responses triggered by OncoTherad® (MRB-CFI-1) therapy applied to BCG-unresponsive patients with carcinoma in situ." (PMID 38139364, 2023).
cardiomyopathy (1 paper, 2025). A disease of the heart muscle or myocardium proper. "In the context of cardiomyopathy induced by T. cruzi infection, the role of the CX3CL1/CX3CR1 axis was not explored until the late 1990s." (PMID 40936920, 2025).
carotid atherosclerosis (1 paper, 2021). A thickening and loss of elasticity of the walls of carotid arteries that occur with formation of atherosclerotic plaques. "The implications of this finding may be clinically relevant, as prior studies have associated augmented expression of CX3CR1 on monocytes to increased carotid atherosclerosis, neuroinflammation, and aging." (PMID 34834941, 2021).
cervical cancer (1 paper, 2024). A primary or metastatic malignant neoplasm involving the cervix. "Based on our findings, we found that CX3CR1 showed reduced expression in cervical cancer." (PMID 38532933, 2024).
chronic rhinosinusitis (1 paper, 2022). Chronic form of sinusitis. "A study on nasal tissue from individuals with allergic and nonallergic chronic rhinosinusitis highlighted a novel role for CX3CR1 (i.e., CX3CR1 may contribute to natural killer cell trafficking to the allergic upper airway)." (PMID 35246242, 2022).
clear cell renal cell carcinoma (1 paper, 2022). "For example, although a four-gene signature (composed of NCR1, PRF1, CX3CL1 and CX3CR1) was shown to accurately distinguish NK-high vs NK-low subgroups in clear cell renal cell carcinoma, these genes are ubiquitously expressed by many immune cell types." (PMID 36685584, 2022).
cocaine addiction (1 paper, 2021). "So, CX3CR1-GFP (CX3CR1−/−) mice could represent a suitable in vivo model to explore the involvement of microglia priming and activation in the development of cocaine addiction." (PMID 34683104, 2021).
contact dermatitis (1 paper, 2020). An inflammatory skin condition caused by direct contact between the skin and either an irritating substance or an allergen. "In conclusion, our results support the notion that macrophages also play an important role in contact dermatitis and that CX3CR1 deficiency might affect the polarization and function of macrophages." (PMID 33036460, 2020).
dermoid cyst (1 paper, 2013). A tumor consisting of displaced ectodermal structures along the lines of embryonic fusion, the wall being formed of epithelium-lined connective tissue, including skin appendages, and containing keratin, sebum, and hair. "The next most common CX3CR1-positive types of cells in the tested cases of dermoid cyst were those comprising the pilosebaceous unit of the skin assembled of sebaceous gland and hair follicle." (PMID 23958497, 2013).
developmental disability (1 paper, 2022). Disorders in which there is a delay in development based on that expected for a given age level or stage of development. "In contrast, CX3C1/CX3CR1 is considered to take part in NKT-cell trafficking within the thymus, but this function may not be of vital importance as CX3CR1-deficient mice do not show NKT-cell developmental disability." (PMID 36389715, 2022).
dyslipidaemia (1 paper, 2025). "In conclusion, we evaluated the activation of the CX3CL1/CX3CR1 axis in subjects with FCH, a human genetic model of mixed dyslipidaemia and IR." (PMID 41153665, 2025).
encephalomyelitis (1 paper, 2024). Inflammation of the brain and the spinal cord. "Conversely, concentrations of the anti-inflammatory cytokine IL-10 are significantly greater in WT mice affected by experimentally induced encephalomyelitis than in CX3CR1−/− mice affected by this disease." (PMID 39062768, 2024). "Moreover, the disease course of CX3CR1−/− mice with experimentally induced encephalomyelitis is more severe than that of WT mice." (PMID 39062768, 2024).
endotoxemia (1 paper, 2016). "Here, our results highlight the importance of the FKN/CX3CR1 signaling axis in retinal microglia function during DR and endotoxemia." (PMID 28119571, 2016). "We speculate based on our results that CX3CR1 contributes to maintaining the integrity of the BRB during endotoxemia, perhaps indirectly by repressing proinflammatory cytokines released from activated microglia and astrocytes that can act on endothelial cells." (PMID 28119571, 2016).
enterocolitis (1 paper, 2018). An inflammatory process affecting the small intestine and colon. "The same study showed that the knock-out of IL-10R in CX3CR1+ macrophages leads to spontaneous enterocolitis." (PMID 29734661, 2018).
enteropathy (1 paper, 2013). "S. TminvG requires CD11c+CX3CR1+ monocytic phagocytes for traversing the epithelial barrier, grows within the LP and elicits enteropathy in a Myd88-dependent fashion by day 3 p.i. in wild type mice." (PMID 24143212, 2013).
Fanconi anemia (1 paper, 2021). Fanconi anemia (FA) is a hereditary DNA repair disorder characterized by progressive pancytopenia with bone marrow failure, variable congenital malformations and predisposition to develop hematological or solid tumors. "Here we identify a hitherto unknown role of CX3CR1 in Fanconi anemia (FA) pathway mediated repair of DNA interstrand crosslinks (ICLs) in replicating cells." (PMID 33810010, 2021). "Here we show for the first time that the clinical-phase small molecule inhibitor KAND567 targeting CX3CR1 augments the efficacy of DNA crosslinking chemotherapeutics in cancer cell lines, including platinum resistant models, by interference of the Fanconi anemia DNA repair pathway." (PMID 33810010, 2021).
Giardia infection (1 paper, 2019). "We show that a population of F4/80+, CD11b+, CD11cint, CX3CR1+, MHCII+, Ly6C−, ARG1+, and NOS2+ macrophages accumulate in the mouse small intestine during Giardia infection." (PMID 31455692, 2019).
Gross hematuria (1 paper, 2015). "Gross hematuria in patients with IgAN correlates significantly with renal expression of FKN and elevation of the number of circulating CX3CR1+ leukocytes." (PMID 26348210, 2015).
hearing loss (1 paper, 2025). "Collectively, the structural and functional synaptic data suggest that the dysfunctional CX3CR1 variant hCX3CR1I249/M280 is associated with worsening of IHC synaptic loss and impedes synapse repair after noise-induced hearing loss." (PMID 40470257, 2025).
hemarthrosis (1 paper, 2020). Bleeding into the joints. "Seemingly, the assessment of the expression of CX3CR1 would be the optimal solution in these patients immediately after the episode of acute hemarthrosis, but conducting such a study would be clearly limited." (PMID 32884948, 2020).
hemochromatosis type 1 (1 paper, 2016). Hemochromatosis type 1 (classic) is the most common form of hereditary hemochromatosis (HH), a group of diseases characterized by excessive tissue iron deposition. "The enrichment overlaps included a known pathogenic missense variant in myeloperoxidase deficiency (MPO), and we identified additional known pathogenic variants in uncurated genes including CX3CR1 (HIV progression) and hemochromatosis type 1 (HFE)." (PMID 27863252, 2016).
hepatic granuloma (1 paper, 2015). A granuloma located in the liver. "In summary, we demonstrated that blockade of Cx3cr1 signaling provides protection for mice against pro-inflammatory responses and hepatic granuloma formation in the setting of acute schistosomiasis." (PMID 26035381, 2015).
hepatitis B virus (1 paper, 2025). "Furthermore, CX3CR1 SNPs are linked to hepatitis B virus (HBV) infection and disease progression, potentially influencing HBV viral load." (PMID 40733585, 2025).
hepatoblastoma (1 paper, 2020). Hepatoblastoma (HB) is a malignant hepatic tumor and is the most common pediatric liver cancer. "The analysis was replicated in two independents cohorts, substantiating that an activation of the CX3CL1/CX3CR1 pathway occurs in hepatoblastomas." (PMID 32432034, 2020). "Altogether, these data suggested that CX3CL1/CX3CR1 upregulation may be a common feature of hepatoblastomas, potentially related to chemotherapy response and progression." (PMID 32432034, 2020). "Overall, we present here novel candidate genes for hepatoblastoma, with evidence that CX3CL1/CX3CR1 chemokine signaling pathway is likely involved with progression, besides reporting specific mutational signatures." (PMID 32432034, 2020).
hepatopulmonary syndrome (1 paper, 2025). Hepatopulmonary syndrome (HPS) is a lung disease characterized by widening of arteries and veins (dilatation) in the lungs in people who have chronic liver disease. "Additionally, interactions between EDNRB and other signaling pathways, such as the C-X3-C motif chemokine ligand 1 (CX3CL1)/C-X3-C motif chemokine receptor 1 (CX3CR1) axis in experimental hepatopulmonary syndrome, underscore the need for caution in therapeutic targeting." (PMID 40597436, 2025).
Hydrocephalus (1 paper, 2024). Hydrocephalus is an active distension of the ventricular system of the brain resulting from inadequate passage of CSF from its point of production within the cerebral ventricles to its point of absorption into the systemic circulation. "T2-weighted imaging suggested that hydrocephalus after IVH was ameliorated by CX3CR1 knockdown and in Cx3cr1-/- mice." (PMID 38505607, 2024). "In contrast, the repair of mLVs was promoted and the effects of hydrocephalus were ameliorated after CX3CR1 knockdown and in Cx3cr1-/- mice." (PMID 38505607, 2024). "Next, we examined whether hydrocephalus after IVH could be alleviated by knockdown of CX3CR1 and in Cx3cr1-/- mice." (PMID 38505607, 2024). "In comparison to the AAV-shRNAcx3cr1+IVH group, the AAV-shRNAnc+IVH group exhibited a significant increase in lateral ventricular volume, suggesting that prior knockdown of CX3CR1 could improve hydrocephalus after IVH." (PMID 38505607, 2024). "CX3CR1 is a key molecule in NET-induced LEC damage and meningeal lymphatic thrombosis, which leads to mLV dysfunction and exacerbates hydrocephalus and brain injury." (PMID 38505607, 2024). "CX3CR1 is a key molecule in NET-induced endothelial damage and lymphatic thrombosis, leading to the dysfunction of mLVs and exacerbating hydrocephalus and brain injury." (PMID 38505607, 2024).
idiopathic thrombocytopenic purpura (1 paper, 2014). "Interestingly, IVIg is used in the treatment of idiopathic thrombocytopenic purpura and increased expression of CX3CR1 has been observed in these patients." (PMID 24655894, 2014).
IgA vasculitis (1 paper, 2024). "Recruitment of CXCR3+ T-cells in the kidney of adult patients with IgA vasculitis correlates with the involvement of the CX3CR1–fractalkine axis in the exacerbation of gross hematuria." (PMID 38791337, 2024).
IgG4-related diseases (1 paper, 2022). "In IgG4-related diseases, CX3CR1-positive cells express cytotoxic molecules." (PMID 35880181, 2022).
immune deficiencies (1 paper, 2025). "Overall, our study revealed an increase in CX3CR1+CD57+ NK and NKT cells in patients with STAT3 mutation and identified the regulatory role of STAT3 in CX3CR1 expression, which explains the immune deficiency observed in these patients." (PMID 41212476, 2025). "In summary, we found that STAT3 influences the differentiation and function of NK and NKT cells by modulating CX3CR1, thereby providing an explanation for the immune deficiencies observed in patients with STAT3 mutations." (PMID 41212476, 2025). "Additionally, we found that STAT3 mutations regulate the phenotype and function of immune cells by modulating CX3CR1 and IL-4, further elucidating the mechanisms of immune deficiency and high IgE levels in patients with STAT3 mutations." (PMID 41212476, 2025).
infertile (1 paper, 2017). "We observed a slight increase CXCR3, CX3CR1 and CCR2 receptors in eNK cells from infertile women positive for HHV-6A infection (p = 0.02; p = 0.012; p = 0.01, respectively; Student’s t-test)." (PMID 29326672, 2017).
intracerebral hemorrhage (1 paper, 2014). A cerebrovascular disorder characterized by bleeding into one or both cerebral hemispheres including the basal ganglia and the cerebral cortex. "Peripherally derived CX3CR1+ monocytes were observed in the perihematomal brain 7 and 14 days after intracerebral hemorrhage." (PMID 25469644, 2014). "We hypothesized that the Ly6Clo CX3CR1+ monocytes would contribute to recovery after intracerebral hemorrhage." (PMID 25469644, 2014). "Intracerebral hemorrhage was modeled by blood injection in WT and CX3CR1-null bone marrow chimeras." (PMID 25469644, 2014). "Our data suggests CX3CR1 signaling on monocytes does not play an influential role in acute injury or functional recovery after intracerebral hemorrhage and therefore CX3CR1 is not a therapeutic target to improve outcome after intracerebral hemorrhage." (PMID 25469644, 2014).
intracranial aneurysms (1 paper, 2022). "Nowiki's study signified that M1‐polarized macrophages are indispensable in the development of intracranial aneurysms owning to their iconic production of including tissue necrosis factor (TNF), Cx3Cr1 and iNOS." (PMID 34970805, 2022).
iron deficiency (1 paper, 2023). "The mRNA expression of the endometrium receptivity-related genes, PR, SOX-17, CX3CR1, FKN, activin, follistatin, BMP2, as well as the examined cytokines and chemokines LIF, IL-6, and IL-1β, were significantly downregulated at DFO-induced iron deficiency in HEC-1A cells." (PMID 37175630, 2023).
ischemia reperfusion injury (1 paper, 2023). Adverse functional, metabolic, or structural changes in ischemic tissues resulting from the restoration of blood flow to the tissue (reperfusion), including swelling; hemorrhage; necrosis; and damage from free radicals. "In the kidney, Cx3cr1 regulates monocyte and macrophage accumulation following ischemia reperfusion injury (IRI); loss of Cx3cr1 is associated with improved kidney function and reduced macrophage accumulation following IRI." (PMID 37256130, 2023).
kidney injury (1 paper, 2021). Trauma to the kidney. "In a different disease scenario, it has also been demonstrated that CX3CR1-dependent mechanisms protect against acute kidney injury in sepsis." (PMID 34163473, 2021). "However, in this model of acute kidney injury, neither treatment with an anti-CX3CR1 neutralising antibody nor genetic CX3CR1 deficiency reduced the peak creatinine level, peak blood urea nitrogen level or macrophage infiltration of the kidney after injury." (PMID 34163473, 2021).